DRG2 (developmentally regulated GTP binding protein 2)
Description:
Catalyzes the conversion of GTP to GDP through hydrolysis of the gamma-phosphate bond in GTP. When hydroxylated at C-3 of 'Lys-21' by JMJD7, may bind to RNA and play a role in translation.
Tractability: PROTAC: UniProt records ubiquitination sites on it; ubiquitination databases record sites on it; its protein half-life has been measured.
Gene: Protein-coding gene on chromosome 17 (18,087,892 to 18,107,979, forward strand). Ensembl gene ENSG00000108591.
Subcellular location: Nucleus; Cytoplasm
Subcellular location (Human Protein Atlas): Cytosol; Vesicles; Nucleoplasm
Pathways (Reactome):
Metabolism of proteins: Protein hydroxylation
Gene Ontology:
Molecular function: GTPase activity; protein binding; RNA binding; GTP binding
Biological process: cytoplasmic translation; signal transduction
Cellular component: cytoplasm; cytosol; membrane; nucleus
Genetic constraint (gnomAD): Loss-of-function variants: 35 observed, 49.79 expected, observed/expected ratio (o/e) 0.7, 90% interval 0.54 to 0.93. The upper end of that interval is the gene's LOEUF score, 0.93, which puts it in group 3 of 6, group 1 being the genes least tolerant of losing a copy. Missense variants: 317 observed, 454.16 expected, observed/expected ratio (o/e) 0.7, 90% interval 0.64 to 0.77. Synonymous variants: 147 observed, 177.74 expected, observed/expected ratio (o/e) 0.83, 90% interval 0.72 to 0.95.
Homologues: Orthologues: chimpanzee DRG2 (100% identical), dog DRG2 (99% identical), guinea pig DRG2 (99% identical), mouse Drg2 (99% identical), pig DRG2 (99% identical), rat Drg2 (99% identical), tropical clawed frog drg2 (95% identical), macaque DRG2 (92% identical), zebrafish drg2 (91% identical), Drosophila melanogaster CG6195 (80% identical), Caenorhabditis elegans C02F5.3 (76% identical). Paralogues in human: DRG1 (57% identical), GTPBP4 (21% identical), GTPBP10 (20% identical), MTG2 (17% identical).